SMAD1 (SMAD family member 1)
Description:
Transcriptional modulator that plays a role in various cellular processes, including embryonic development, cell differentiation, and tissue homeostasis. Upon BMP ligand binding to their receptors at the cell surface, is phosphorylated by activated type I BMP receptors (BMPRIs) and associates with SMAD4 to form a heteromeric complex which translocates into the nucleus acting as transcription factor. In turn, the hetero-trimeric complex recognizes cis-regulatory elements containing Smad Binding Elements (SBEs) to modulate the outcome of the signaling network. SMAD1/OAZ1/PSMB4 complex mediates the degradation of the CREBBP/EP300 repressor SNIP1. Positively regulates BMP4-induced expression of odontogenic development regulator MSX1 following IPO7-mediated nuclear import (By similarity).
Synonyms: BSP-1; BSP1; MADH1; MADR1; JV4-1; JV41
Tractability: Small molecule: it has a high-quality binding pocket. PROTAC: UniProt records ubiquitination sites on it; ubiquitination databases record sites on it; its protein half-life has been measured.
Gene: Protein-coding gene on chromosome 4 (145,480,769 to 145,559,176, forward strand). Ensembl gene ENSG00000170365.
Subcellular location: Cytoplasm; Nucleus
Subcellular location (Human Protein Atlas): Cytosol; Nucleoplasm
Pathways (Reactome):
Developmental Biology: Cardiogenesis; Transcriptional regulation of brown and beige adipocyte differentiation by EBF2
Gene expression (Transcription): RUNX2 regulates bone development
Metabolism of proteins: Ub-specific processing proteases
Signal Transduction: Signaling by BMP
Gene Ontology:
Molecular function: co-SMAD binding; DEAD/H-box RNA helicase binding; DNA-binding transcription activator activity, RNA polymerase II-specific; DNA-binding transcription factor activity; DNA-binding transcription factor activity, RNA polymerase II-specific; I-SMAD binding; identical protein binding; protein binding; protein kinase binding; RNA polymerase II cis-regulatory region sequence-specific DNA binding; ubiquitin protein ligase binding; primary miRNA binding; sequence-specific DNA binding
Biological process: anti-Mullerian hormone receptor signaling pathway; BMP signaling pathway; DNA-templated transcription; intracellular iron ion homeostasis; ossification; osteoblast differentiation; positive regulation of sprouting angiogenesis; positive regulation of transcription by RNA polymerase II; SMAD protein signal transduction; transforming growth factor beta receptor signaling pathway; anatomical structure morphogenesis; cardiac conduction system development; cell differentiation; embryonic pattern specification; positive regulation of dendrite development; primary miRNA processing; regulation of transcription by RNA polymerase II; signal transduction; stem cell differentiation; cellular response to growth factor stimulus; developmental process; inflammatory response; positive regulation of miRNA transcription; regulation of DNA-templated transcription; transforming growth factor beta receptor superfamily signaling pathway; and 1 more
Cellular component: chromatin; cytoplasm; cytosol; heteromeric SMAD protein complex; homomeric SMAD protein complex; nuclear inner membrane; nucleoplasm; nucleus; protein-containing complex; membrane; SMAD protein complex; transcription regulator complex
Genetic constraint (gnomAD): Loss-of-function variants: 5 observed, 37.44 expected, observed/expected ratio (o/e) 0.13, 90% interval 0.069 to 0.28. The upper end of that interval is the gene's LOEUF score, 0.28, which puts it in group 1 of 6, group 1 being the genes least tolerant of losing a copy. Missense variants: 358 observed, 586.57 expected, observed/expected ratio (o/e) 0.61, 90% interval 0.56 to 0.67. Synonymous variants: 191 observed, 204.04 expected, observed/expected ratio (o/e) 0.94, 90% interval 0.83 to 1.05.
Gene-disease validity (ClinGen):
ClinGen rates the evidence that SMAD1 causes each of these diseases.
congenital heart disease (autosomal dominant): Limited. A heart disease that is present at birth.
pulmonary arterial hypertension (autosomal dominant): Disputed. Pulmonary arterial hypertension (PAH) is a group of diseases characterized by mean pulmonary artery pressure >20 mmHg and elevated pulmonary arterial resistance leading to right heart failure.
Homologues: Orthologues: macaque SMAD1 (100% identical), pig SMAD1 (99% identical), dog SMAD1 (99% identical), mouse Smad1 (99% identical), chimpanzee SMAD1 (99% identical), guinea pig SMAD1 (99% identical), rat Smad1 (99% identical), rabbit SMAD1 (98% identical), tropical clawed frog smad1 (96% identical), zebrafish smad1 (90% identical). Paralogues in human: SMAD5 (91% identical), SMAD9 (81% identical), SMAD2 (61% identical), SMAD3 (61% identical), SMAD4 (40% identical), SMAD6 (26% identical), SMAD7 (25% identical).
Diseases named in the same sentence as SMAD1 in open-access papers:
SMAD1 is named in the same sentence as 199 diseases in open-access papers, as found by Europe PMC text mining. Sharing a sentence is not in itself a finding about the gene and the disease. The quoted sentences say what the papers report.
breast cancer (29 papers, 2008 to 2025). A primary or metastatic malignant neoplasm involving the breast. "Increased BMPR-IB (a protein of TGF-β pathway) expression leads to a deregulated SMAD1 activity, which was already reported to be associated with an increase in breast cancer progression." (PMID 31487369, 2020). "Mechanistically, we showed that these metastasis-related processes are functionally linked to MEK/ERK/SMAD1 cascade activation in breast cancer cells." (PMID 30674353, 2019). "The important role of the balance of shed and cell surface TβRIII for Smad1/5 signaling has been studied in breast cancer models." (PMID 33772427, 2021). "Accordingly, either the inhibition of MEK or SMAD1 impacts on the expression of MG stress pro-metastatic signature and decreases the migratory potential of breast cancer cells." (PMID 30674353, 2019). "We further analyzed the relevance of BMP4 or SMAD1 mRNA levels in primary breast cancer with bone-specific metastasis based on the GSE2034_GSE2603 data set." (PMID 31222004, 2019). "MEK and SMAD1 regulation of MG pro-metastatic signature genes in breast cancer cells was demonstrated by RT-qPCR." (PMID 30674353, 2019). "MDA-MB-468 cells, which are considered as high SMAD1 expressers when compared with other breast cancer cell lines, showed a similar pattern of SMAD1 serine phosphorylation upon MG treatment." (PMID 30674353, 2019). "Consistent with this notion, we found that BMP-induced SMAD1/5 phosphorylation is inhibited in breast cancer cells and in CAFs." (PMID 31533776, 2019). "In mice treated with halofuginone (1 and 5μg/day) there was an inhibition of BMP signaling activity in breast cancer cells in bone as measured by phospho-Smad1/5/8-positive nuclei." (PMID 29156807, 2017). "Consistent with the in vitro data, tumors of mice with breast cancer bone metastasis had a reduction in phospho SMAD1/5/8-positive nuclei, suggesting an inhibition of BMP signaling in the bone metastatic microenvironment of mice treated with halofuginone." (PMID 29156807, 2017). "Intense Smad1 phosphorylation has been observed not only in the Snail-overexpressing cells in our study but also in metastatic tumor tissues derived from breast cancer." (PMID 25003810, 2014). "We observed prominent Smad1/3 phosphorylation in Ras-induced mammary tumors, confirming our computational prediction that the TGFβ pathway remains activated in Ras-induced tumors." (PMID 19094238, 2008). "LDN-193189 is a selective BMP signaling inhibitor that inhibits the kinase activity of ALK2 and the related ALK1 and at a concentration of 1 μM has been shown to also partially and selectively inhibit TGFβ-induced SMAD1/5C phosphorylation in the breast cancer cell line, MDA-MB-231." (PMID 36289908, 2022). "However, transient SMAD1/5 phosphorylation is not a defining characteristic of this arm of TGF-β signaling, as another human breast cancer line, BT-549, exhibited sustained SMAD1/5 phosphorylation that is still readily detectable 8 hr after TGF-β stimulation." (PMID 29376829, 2018). "However, BMP2 has been shown to inhibit proliferation in breast cancer cell lines that express SMAD1 and SMAD4." (PMID 22729646, 2012). "Phosphorylated Smad-1/5, located in the nucleus, was detected in tumors derived from clones expressing high levels of BMPs, indicating an active BMP signaling pathway and BMP-2 stimulation of mammary tumor cell clones in vitro resulted in activation of the Smad-1/5 pathway." (PMID 19771160, 2009). "Thus, whether the G9a-knockdown-induced increase in BMP5 expression influences Smad1/5/9 phosphorylation in breast cancer cells needs to be elucidated." (PMID 35054776, 2022). "Conversely, its downregulation in breast cancer and/or osteosarcoma leads to increased levels of connective tissue growth factor (CTGF) and Smad1, promoting metastasis." (PMID 41562703, 2025).
breast cancer (continued). "SMAD4, SMAD2, SMAD3, SMAD7, SMAD1, SMAD6, and SMAD5 showed genetic variation in 1.8%, 1.2%, 1.1%, 0.8%, 0.7%, 0.6%, and 0.5% of patients with breast cancer, respectively." (PMID 38514720, 2024). "To characterise the BMP4 responses, we predominantly used the human breast cancer cell line MDA-MB-231 and the mouse fibroblast cell line NIH-3T3, both of which induce robust SMAD1/5 phosphorylation in response to BMP4." (PMID 31217285, 2019). "TFDP1 is involved in the cell cycle and contributes to hepatocellular carcinomas, SMAD1 is involved in multiple pathways, and QSOX1 plays roles in some cancers such as breast cancer and neuroblastoma." (PMID 29686831, 2018). "We further examined the signaling properties of AB215 in human MCF7 breast cancer cells and found that, similar to what was observed in C2C12 cells, AB215 produces prolonged and enhanced SMAD1/5/8 phosphorylation when compared to that induced by BMP2." (PMID 25070479, 2014). "Systemic administration of BMP7 in breast cancer mouse models has proven to significantly inhibit bone metastases originating from human prostate and breast cancer, by reducing TGFβ-dependent SMAD3/4 activation, activating nuclear signaling of SMAD1/4/5, and restoring E-cadherin levels." (PMID 31547567, 2019). "Using the human breast cancer cell line MDA-MB-231 and the mouse mammary epithelial cell line NMuMG as model systems, we found that TGF-β induced only transient phosphorylation of SMAD1/5 that peaked at 1 hr and then returned to baseline." (PMID 29376829, 2018). "The transience of SMAD1/5 phosphorylation is not a defining characteristic of this arm of TGF-β signaling as BT-549 breast cancer cells exhibit a more sustained response, which is even more pronounced when the cells are grown as spheres." (PMID 29376829, 2018). "We also used a reporter construct consisting of the phospho-SMAD1/5/8 responsive ID1 promoter upstream of a luciferase gene to compare the effects of BMP2 and AB215 treatment on the human breast cancer cell lines MCF7, T47D and SK-BR-3 in the absence or presence of E2 treatment." (PMID 25070479, 2014). "Notably, sEV TGF‐β+ did not significantly affect the closely related bone morphogenetic protein (BMP)‐SMAD1/5 signalling in breast cancer cells, nor did it impact the interleukin 6 (IL‐6)/signal transducer and activator of transcription 3 (STAT3) signalling." (PMID 40091448, 2025). "Likewise, SMAD1 is negatively correlated with brain-specific relapse and expressed at slightly lower levels in basal-like tumors, while Nuclear Receptor Binding Factor 2 (NRBF2) is positively correlated with brain-specific relapse and expressed at similar levels across breast cancer subtypes." (PMID 32143622, 2020). "On the other hand, Reverse Phase Protein Array (RPPA) data for the breast cancer patient cohort, where it is possible to analyze the change in β-CATENIN protein level, did not include either BMP2/BMP6 or phosphorylated SMADs (SMAD1/SMAD5) or direct target genes of BMP pathway such as ID1–3." (PMID 38731813, 2024).
prostate carcinoma (18 papers, 2012 to 2025). A carcinoma that arises from epithelial cells of the prostate gland. "In prostate cancer, it hinders tumor proliferation and invasion through downregulation of Smad1, and it is notably diminished in cancer stem cells." (PMID 41154751, 2025). "This study was intended to analyze effects of miR-199a-3p and Smad1 on proliferation, migration and invasion of prostate cancer (PCa) cells." (PMID 28881744, 2017). "BMP-9 has also been shown to activate the ALK2/Smad1/Smad4 and the ALK4/Smad1 pathways to promote ovarian cancer cell proliferation and to cause apoptosis in prostate cancer cells." (PMID 27650540, 2016). "Smad1 has been identified as a corepressor for AR and inhibits proliferation of androgen dependent prostate cancer cells." (PMID 23734213, 2013). "In this study, we determined the functional domains of p44 responsible for protein-protein interaction with AR and Smad1 transcription factors, transcriptional activation, as well as the functional domains related to growth inhibition in prostate cancer." (PMID 23734213, 2013). "In prostate cancer cells, miR-199-3p reduced invasion and proliferation via targeting Smad1." (PMID 34123589, 2021). "Additionally, Endoglin, a transforming growth factor beta superfamily auxiliary receptor, was shown to inhibit prostate cancer motility via activation of the Alk2/Smad1 pathway, and BMP7 inhibition of epithelial-to-mesenchymal transition was lost when Alk2 were knocked down in a melanoma cell line." (PMID 22457812, 2012). "In prostate cancer, HOXD13 binds to the SMAD1 promoter, disrupting BMP4-induced EMT and reducing tumor cell invasiveness." (PMID 39744569, 2025). "In fact, ENG suppresses prostate cancer cell migration and invasion via the ALK2/SMAD1 pathway, and it inhibits tumor growth and metastasis in vivo, suggesting that ENG is a negative regulator of prostate cancer." (PMID 33804796, 2021). "Among these six, HLF, JUN, c-MYC, EGR1, SMAD1, and HIF1A, were also identified as PTEN-controlled TFs, and four, ESR2, MYB, RELA, and USF1, as prostate cancer-related TFs." (PMID 22347425, 2012). "In vitro, breast and prostate cancer cells treated with halofuginone showed inhibition of BMP signaling demonstrated by inhibition of BMP-responsive promoter, inhibition of Phospho-Smad1/5/8 and reduction of ID1, a regulator of cancer cell growth and migration." (PMID 29156807, 2017). "PI3K/Akt-NF-kappaB signaling may promote prostate cancer (PC) bone metastasis in part by regulating transcription and activation of BMP2 and subsequent phosphorylation of Smad1/5/8 which are critical downstream targets of BMP2 signaling." (PMID 25938545, 2015).
hepatocellular carcinoma (17 papers, 2016 to 2026). A malignant tumor that arises from hepatocytes. "Smad1 has been identified as a target of miR-26b-5p in hepatocellular carcinoma metastases and during EMT, supporting its involvement in EMT-driven metastatic progression across multiple cancer types." (PMID 41011506, 2025). "The results of these experiments showed that the phosphorylation level of SMAD1 in hepatoma cells was markedly decreased under the influence of PPM1H." (PMID 37456776, 2023). "Our previous study demonstrated a novel function of proHp in Smad1/5 activation in endothelial cells; therefore, we investigated the effect of proHp on the Smad1/5 pathway during the EMT in hepatoma cells." (PMID 35580109, 2022). "Next, we tested the active fraction for effect on a BMP2-induced SMAD1/5-dependent transcriptional reporter (BRE-luc) assay in HepG2 hepatocellular carcinoma cells." (PMID 32820031, 2020). "TWIST1 downregulates miR-26b-5p in hepatocellular carcinoma by binding to its promotor region, thereby unchecking Smad1 expression and deregulating BMP4/Smad1 signaling, which promotes EMT." (PMID 29112161, 2017). "Conversely, the decreased levels of p‐Smad1/5/8 and Smad6 following the increased level of p‐Smad3 were abolished in the HUVECs pre‐incubated with BMP9‐overexpressing HBV‐infected hepatoma cells." (PMID 37132170, 2023). "A significant decrease in the p‐Smad1/5/8 and Smad6 levels following the increase in the p‐Smad3 level was detected in the HUVECs pre‐incubated with HBV‐infected hepatoma cells compared with those pre‐incubated with HBV‐uninfected hepatoma cells." (PMID 37132170, 2023). "A detailed further study is required to verify the interaction and crosstalk between the two TGF-β signaling pathways through Smad2/3 activation and Smad1/5/8 activation during EMT induction and metastasis of hepatoma cells." (PMID 35580109, 2022). "SMAD1 is best characterized for activating ID1, which promotes proliferation and confers drug resistance in hepatocellular carcinoma, colon cancer, lung cancer, and acute myeloid leukemia." (PMID 34134766, 2021). "In the hepatocellular carcinoma cell line HepG2, BMP9 induces phospho-Smad1/5/8 phosphorylation leading to increased survival." (PMID 34771575, 2021). "In this study, PPM1H inhibited phosphorylation of SMAD1 and RPS6KB1 in hepatoma cells." (PMID 37456776, 2023). "For example, a direct cross talk between Smad3 and STAT3 is bridged by p300 in hepatoma cells, a synergistic action of LIF-induced-Smad1 and BMP2-induced-STAT3 is bridged by p300 in neural cells, and Smad2/3 and STAT3 cooperatively interact in Th17 cell differentiation." (PMID 29963056, 2018). "Interestingly, overexpressing PPM1H still inhibited Transwell migration and invasion of Hep-G2 and Huh-7 cells after blocking phosphorylation of SMAD1 with LDN193189, pointing to the fact that there might be other substrates of PPM1H that regulate hepatoma cell growth and invasion." (PMID 37456776, 2023).
pulmonary arterial hypertension (14 papers, 2015 to 2025). "Recently, reports showed that Tacrolimus, an inhibitor of mTOR, was associated with increased Smad1/5/8 signaling in cultured Alk1 knock-down endothelial cells and in an Alk1−/+ mouse model of HHT and pulmonary arterial hypertension." (PMID 39899215, 2025). "Rare variants such as SMAD1, SMAD4, and SMAD9 associated with genetics with pulmonary arterial hypertension are also located in the cytoplasm and nucleus." (PMID 40710838, 2025). "Interestingly, lung BMPRII and phosphorylated SMAD1/5/8 levels were found to be decreased in a model of pulmonary hypertension associated with pulmonary fibrosis, suggesting that SMAD signaling balance might coordinately regulate fibrosis together with cell proliferation." (PMID 35141256, 2021). "In addition, Pulmonary Arterial Hypertension (PAH) is associated with reduced BMPRII or SMAD1 function." (PMID 29230182, 2017). "In addition, prostacyclin can inhibit the proliferation of smooth muscle cells, thereby preventing the progression of pulmonary hypertension and increase Smad1/5 phosphorylation and Id1 expression." (PMID 29348884, 2017). "Inhibition of BMP9 can downregulate Smad1/5 via ALK-1 thereby downregulating ATOH8, promoting HIF-2α expression and exacerbating hypoxia in pulmonary hypertension." (PMID 39578779, 2024). "BMPR1A and SMAD1 in our gene set are two core components in BMP pathway, which has shown to be related to pulmonary arterial hypertension and vascular calcification." (PMID 25958224, 2015). "In the past 5 years, miR-23a has been found to be a biomarker for idiopathic PH and a possible therapeutic target for pulmonary arterial hypertension because it promotes cell proliferation and migration by targeting the BMPR2/Smad1 signal in hypoxia-induced PASMCs." (PMID 34374413, 2021).